IL17A (interleukin 17A)
Diseases named in the same sentence as IL17A in open-access papers (continued):
Sharing a sentence is not in itself a finding about the gene and the disease.
colorectal cancer (continued). "Blocking IL-17A leads to a significant reduction of tumor growth in murine models of gastric cancer, prostate cancer, colorectal cancer, myeloma, and other type of cancer." (PMID 39906741, 2024). "The colorectal cancer cells were treated with IL-17A, and the morphological characteristics of those cells were indicated by scanning electron microscope and transmission electron microscope." (PMID 37211606, 2023). "In both colorectal cancer and lung cancer, IL-17A can recruit antitumour neutrophils, stimulating a T-cell response in the tumour immune microenvironment, which correlates with better overall survival." (PMID 37211606, 2023). "Research shows that IL-17A inhibitors have preventive potential in human cancers, particularly colorectal cancer." (PMID 36823571, 2023). "In this study, the mechanism of IL-17A that induces mitochondrial dysfunction promoted pyroptosis has been explored in colorectal cancer cells." (PMID 37211606, 2023). "Increased expression of vascular endothelial growth factor and micro-vessel density in colorectal cancers have been related to increased levels of IL-17A, indicating a connection between IL-17A and angiogenesis." (PMID 38137417, 2023). "To investigate the biological function of IL-17A, we screened for the highest IL-17R expression and selected the colorectal cancer cell line SW620." (PMID 37211606, 2023). "Vγ4 and Vγ6TCR γδ T cells have been reported to promote the growth of colorectal cancer by producing IL-17A." (PMID 37939119, 2023). "To investigate the effect of IL-17A on colorectal cancer cells, we observed the morphology of the cells with a microscope." (PMID 37211606, 2023). "We considered that IL-17A was an important bridge between inflammation and immunity in colorectal cancer, the relationship between IL-17A and antitumour immunity is worthy of further investigation." (PMID 37211606, 2023). "For MSS colorectal cancer, it has been proved that combined blocking of IL-17A and PD-1 can better block the occurrence of colorectal cancer." (PMID 38273841, 2023). "Our study found that IL-17A signalling can induce inflammatory death of colorectal cancer cells, releasing considerable immune antigens through cell pyroptosis and consequently recruiting CD8 + T-cell to activate tumour immunity." (PMID 37211606, 2023). "The goal of this study was to investigate the cascade response induced in tumour cells in response to IL-17A in human colorectal cancer." (PMID 37211606, 2023). "Early studies have suggested that IL-17A can promote proliferation, migration, invasion, and resistance to chemotherapy-induced cell death in breast and colorectal cancer." (PMID 37686343, 2023). "To further substantiate the results, we randomly selected six paired samples from colorectal cancer patients and performed Western blot analysis of IL-17A expression." (PMID 37211606, 2023). "The finding of a correlation between Prevotella and the cytokines IL-5, IL-9 and IL-17A in the tumour microenvironment in colorectal cancer confirms a bidirectional interference between the host immune response and microbiota." (PMID 36407282, 2023). "In this study, we found a possible mechanism by which IL-17A regulates pyroptosis in colorectal cancer cells and mitochondrial dysfunction." (PMID 37211606, 2023). "Prevotella's lipopolysaccharides (LPS) have a proinflammatory effect and its abundance is negatively correlated with interleukin (IL)-17A in colorectal cancer samples while the correlation with IL-9 is positive." (PMID 35372388, 2022). "Interleukin-17A mRNA is a protective factor in colorectal cancer and a promising biomarker for assessing the prognosis and immunotherapeutic response." (PMID 36098359, 2022). "This Treg subset secreted IL-17A and promoted the progression of colorectal cancer by exhausting CD8+ T cells." (PMID 35948909, 2022). "The aim of our study was to assess the prognostic role of interleukin-17A in colorectal cancer and determine the potential mechanisms." (PMID 36098359, 2022).
colorectal cancer (continued). "PLA2G4A activates the colorectal cancer microenvironment to produce pro-cytokines IL-17A and adenosine, thereby establishing an effective immunosuppressive microenvironment and promoting immune evasion and tumor metastasis." (PMID 36120336, 2022). "The GEO database was searched using the keyword “colorectal cancer”, and 10 datasets were identified that included interleukin-17A mRNA expression and survival data of several colorectal cancer patient cohorts." (PMID 36098359, 2022). "Besides IL-1α, IL-17A was linked with disease-free survival in patients with colorectal carcinoma (CRC), potentially serving as a surrogated marker in combination with CTC in CRC." (PMID 35966579, 2022). "IL-1α and IL-1β in the tumor microenvironment play critical roles in colorectal cancer growth by inducing tumor-elicited inflammation through IL-17A and IL-22 production in T cells." (PMID 33406733, 2021). "Previous studies have reported that overexpression of IL17A means poor survival in colorectal cancer patients." (PMID 32457797, 2020). "In murine colorectal cancer model, forced expression of β-catenin in CD4+ T cells caused increased IL-17A expression that favor tumor progression." (PMID 32132993, 2020). "IL-17A-producing CD4+ T (Th17) cells play an important role in the pathogenesis of colorectal cancer." (PMID 32132993, 2020). "In our clinical trial, circulating inflammatory cytokines of TNF-α, IL-10, IL-12, IL-17A, IL-17C and IL-22 remained high in colorectal cancer patients even after removal of tumor." (PMID 31340751, 2019). "Interleukin-17A (IL-17A) secreted by chemotherapy-treated human CAFs promoted the colorectal cancer initiating cell (CIC) self-renewal and tumor growth displaying the conventional chemotherapy resistance features." (PMID 30680600, 2019). "A study has revealed that proportions of Th1 and Th17 cells and cytokines, IL-17A, IL-22, and IL-23A, produced by Th17 cells are higher in conventional mice than in GF mice when fed with stool from patients with colorectal cancer." (PMID 31687412, 2019). "Anti-IL-17A inhibitors play a substantial role in development of anti-cancer drugs for colorectal cancer." (PMID 30304852, 2018). "Using spontaneous intestinal carcinogenesis models, the role of IL-17A in colorectal cancer development was further elucidated." (PMID 28492497, 2017). "They showed that significantly higher IL-17A concentrations were found at early colorectal cancer stages (I/II) concomitantly with increased concentrations of Il-23, another interleukin linked to Th17 differentiation, compared to control healthy donors." (PMID 28347290, 2017). "According to the literature, IL-17A is involved in colorectal cancer progression, in cancer resistance and tumor escape following anti-VEGF-based therapy." (PMID 28347290, 2017). "In an adoptive transfer model, enforced expression of β-catenin in intratumoral CD4+ T cells increased IL-17a expression, enhanced proliferation and inhibited apoptosis of colorectal cancer cells." (PMID 28147310, 2017). "It should to be noted that the expression of proinflammatory cytokines such as IL-17A, IL-6, IL-22 was dramatically increased in lesions of colorectal cancer and their high expression significantly correlated with cancer progression and poor prognosis." (PMID 28811578, 2017). "IL-17A, IL-17 F, and IL-22 are identified to promote the tumorigenesis of colorectal cancer in early studies." (PMID 28063002, 2017). "Hereafter, we suggest that IL17A G197A, IL17F rs763780and IL23R rs10889677 polymorphisms are associated with the development and progression of colorectal cancer." (PMID 26083022, 2015). "The purpose of the present work is to investigate an association between IL17A, IL17F and IL23R polymorphisms in 102 Tunisian patients with colorectal cancer treatment." (PMID 26083022, 2015).
colorectal cancer (continued). "Previously, we showed that there is a significant association between IL17A, IL17F and IL23R polymorphisms as well as the occurrence of colorectal cancer and the clinical features of the disease." (PMID 26083022, 2015). "In light of these results, we additionally studied the association between polymorphisms in IL17F, IL17A and IL23R genes and different types of colorectal cancer treatment." (PMID 26083022, 2015). "Similarly, in colorectal cancer, IL-17A increases resistance to anti-PD-1 therapy by upregulating PD-L1 (programmed death-ligand 1) expression through the P65/nuclear respiratory factor 1/miR-15b-5p axis." (PMID 40536951, 2026). "Preliminary data indicate that IL-17RA overexpression upregulates IL-17A expression in colorectal cancer cells, suggesting the presence of an autocrine loop that could enhance receptor signaling (Data not shown)." (PMID 41438576, 2026). "Recent clinical research has indicated that high IL-17A levels in early-stage colorectal cancer (stage I or II) correlate strongly with rapid tumor progression and metastasis, suggesting that IL-17A could serve as a reliable prognostic biomarker." (PMID 40536951, 2026). "Still, the weak overall fit highlights that while IL-17A may have a minor role in modulating IL-8 expression, other biological factors likely play a more dominant role in driving IL-8 levels in colorectal cancer." (PMID 40725273, 2025). "IL-17A plays a pivotal role in promoting the epithelial–mesenchymal transition, facilitating cellular migration and invasion, particularly in advanced stages of colorectal cancer." (PMID 40725273, 2025). "The diminished IL-17A response in higher-grade tumors may reflect immune suppression or altered cytokine signaling in more advanced disease states, highlighting the interconnected roles of IL-8, IL-17A, and IL-33 in colorectal cancer." (PMID 40725273, 2025). "Considering the critical role of biomarkers in understanding the molecular biology of colorectal cancer, in the present study we examined the expression levels of IL-8, IL-17A, and IL-33 in relation to tumor grade and invasion, while also evaluating the correlations between these three interleukins." (PMID 40725273, 2025). "In addition, miR-15b-5p was downregulated by nuclear respiratory factor 1 (NRF1), a transcription factor enriched in colorectal cancer, which is promoted by the elevated levels of interleukin IL-17A." (PMID 38339019, 2024). "Moreover, reduced expression of RORC and Il17A was correlated with poorer survival outcomes in colorectal cancer patients." (PMID 39669566, 2024). "IL-17A is also an important bridge between inflammation and immunity, and it can induce mitochondrial dysfunction by stimulating intracellular ROS production, thereby promoting pyroptosis, as shown in a colorectal cancer study." (PMID 37895262, 2023). "Our data suggest that IL-17A-mediated mitochondrial dysfunction activates pyroptosis in colorectal cancer cells and promotes CD8 + T-cell infiltration into the tumour, which could be the key cause of the prognostic and regulatory potential." (PMID 37211606, 2023). "Moreover, Z-LEVD, but not Z-YVAD, significantly reversed the induction of pyroptosis in colorectal cancer cells by IL-17A treatment." (PMID 37211606, 2023). "Future studies might elucidate more comprehensive mechanisms underlying the regulation of tumour development and progression in colorectal cancer under conditions of IL-17A treatment." (PMID 37211606, 2023). "By observing the ultrastructure of IL17A-treated colorectal cancer cells, we found numerous pores or pits of varying sizes on the cell membrane, structural collapse, flattening of the cell shape, disruption of the mitochondrial cristae, and rupture of the plasma membrane after IL17A treatment." (PMID 37211606, 2023).
colorectal cancer (continued). "When colorectal cancer cells were stimulated with 100 ng/mL IL-17A for 72 h, numerous pores of varying sizes were distributed over the entire cell surface, and typical characteristics of pyroptosis, including cell swelling and large bubbles on the surface of the cell membrane, were observed." (PMID 37211606, 2023). "IL-17A promotes tumor immunosuppression and induces immune escape in colorectal cancer." (PMID 37444399, 2023). "Western blot results suggested that IL-17A decreases the expression of components of the OxPhos complex, which may lead to an impaired respiratory capacity of the mitochondria in colorectal cancer cells." (PMID 37211606, 2023). "We used scanning electron microscopy to observe the membrane morphology to determine whether IL-17A induces colorectal cancer cell pyroptosis." (PMID 37211606, 2023). "Notably, the presence of F. nucleatum has been correlated with an increase in the IL-17A production and in the frequency of intestinal Th17 cells in colorectal cancer." (PMID 36713516, 2022). "While no anti-human IL-10 antibody has been approved for cancer treatment, the production of IL-17A and adenosine could be targeted in tumors that are highly infiltrated by pro-tumor γδ T cells, such as breast and colorectal cancer." (PMID 33042132, 2020). "Additionally, IL-17A+FoxP3+ T cells are found in colorectal cancer human tissue samples, and have been demonstrated to induce colorectal cancer associated cell markers." (PMID 31681327, 2019). "Furthermore, IL-17 was shown to promote angiogenesis and colorectal tumorigenesis in human colorectal cancer cells and ablation of IL-17A significantly reduced tumor development in mice." (PMID 31780866, 2019). "However, tissue-derived IL-17A, which can recruit myeloid-derived suppressor cells (MDSCs), was reported to energetically participate in the immunosuppression milieu in human colorectal cancer." (PMID 29850635, 2018). "Finally, it should be remarked that RANTES/CCL5 is also known to be induced by chitinases, while CHI3L1 can induce macrophage recruitment by MCP-1 chemotaxis in colorectal cancer and has a role in IL-17A-dependent mechanisms." (PMID 29892291, 2018). "Due to the well-described implication of IL-17A in colorectal cancer, targeting of IL-17A may serve as a promising therapeutic approach." (PMID 28492497, 2017). "In contrast to IL-17A and C, IL-17F is significantly downregulated in human colorectal cancer." (PMID 28492497, 2017). "A recent meta-analysis following Prisma guidelines emphasizes the fact that high IL-17A quantities were correlated with poor prognosis in cancer and notably in colorectal cancer but the impact of high Th17 cell frequencies is very controversial and depends on the cancer type." (PMID 28347290, 2017). "Recently, we hypothesized that Th17 cells can contribute to carcinogenesis and that IL17A, IL17F and IL23R polymorphisms can affect the susceptibility to colorectal cancer." (PMID 26083022, 2015). "For this purpose, the IL17A/F has been suggested as a new prognostic indicator in patients with colorectal cancer and could be considered as a new therapeutic target for colorectal cancer." (PMID 26083022, 2015). "Our results suggest that polymorphisms in IL17A and IL17F genes may be a predictive source of colorectal cancer therapy type." (PMID 26083022, 2015). "Through case / control studies, we have recently showed that unlike IL17F rs763780 and IL23R rs10889677 polymorphisms, IL17A G197A polymorphism is associated with its susceptibility to colorectal cancer." (PMID 26083022, 2015). "Furthermore, a study revealed that IL-17A induces mitochondrial dysfunction in colorectal cancer cells by activating the ROS/NOD-like receptor protein 3/caspase-4/gasdermin D pathway, stimulating intracellular ROS production and promoting tumor cell pyroptosis." (PMID 40536951, 2026).
colorectal cancer (continued). "However, in the CPC-APC (CDX2Cre-Apcf/wt) colorectal cancer model, specific deletion of IL-1R1 in myeloid cells (CD11bCre-Il1r1f/f) resulted in a higher tumor load and stronger inflammatory responses, such as increased IL-17A expression." (PMID 40767963, 2025). "Furthermore, IL-17A could promote pyroptosis of colorectal cancer cells and significantly increase the secretion of inflammatory factors." (PMID 37211606, 2023). "An increasing number of studies and meta-analyses have been performed to explore associations between the IL-17A rs2275913 and IL-17F rs763780 polymorphisms and various types of malignant tumors in recent years; however, the related findings for colorectal cancer display no consensus." (PMID 35410225, 2022). "Notably, the use of IL-17A-blocking antibodies could slow the progression of AOM-DSS-induced colorectal cancer and reduce the susceptibility to colorectal cancer in MondoA-deficient mice." (PMID 36569832, 2022). "Some reports indicated that IL-17A could initiate and favour the tumoral progression at early colorectal cancer stages so it could be interesting to evaluate the impact of IL-17A concentrations at this time in future prospective studies including bevacizumab treatment." (PMID 28347290, 2017). "Moreover, this study aims at evaluating the possible interaction between IL17A G197A, IL17F rs763780 and IL23Rrs10889677 polymorphisms as well as the treatment of colorectal cancer in Tunisian population such as the overall survival of patients with and without treatment." (PMID 26083022, 2015). "IL-17A was shown to stimulate vascular endothelial growth factor A (VEGFA) production and promote angiogenesis in gastric and colorectal cancers." (PMID 37444399, 2023). "Knockdown of IL-21, which is overexpressed in human colorectal cancer and CAC mice, can reverse the overexpression of IL-6 and IL-17A in CAC mice." (PMID 36339623, 2022). "Th17-IL-17 pathway plays a key role in prostate cancer progression, targeting IL17 pathway could prevent micro-invasive prostate cancer in a mouse model, and blocking IL-17A enhances tumor response to anti-PD-1 immunotherapy in microsatellite stable colorectal cancer." (PMID 35902909, 2022). "IL-17A is produced by Th17 cells and ILC3 and plays an important role in both induction of tissue inflammation, anti-microbial immunity, and colorectal cancer." (PMID 30761142, 2019). "In vitro study indicated that colorectal cancer cells suppressed IFN-γ expression and increased IL-17a expression in activated CD4+ T cells." (PMID 28147310, 2017). "In summary, this analysis reveals a significant, non-linear correlation between IL-8 and IL-17A in colorectal cancer, modulated by the type of tumor infiltration." (PMID 40725273, 2025). "We focused on pyroptosis mediated by IL-17A in colorectal cancer cells but did not further explore the exact mechanisms by which pyroptosis influences tumour-infiltrating T cells in the tumour immune microenvironment." (PMID 37211606, 2023). "Therefore, we proposethat IL-17A activates the NF-κB pathway, triggering the activation of caspase-4 and the cleavage of GSDMD in colorectal cancer cells." (PMID 37211606, 2023). "All the other publications reported that IL-17A high expression (RNA, immunohistochemistry and/or serum concentration) is a negative prognostic marker of colorectal cancer progression." (PMID 28347290, 2017). "The non-linear correlation between IL-8 and IL-17A further reflects the complexity of cytokine-mediated immune responses in colorectal cancer progression and supports the potential of IL-8 and IL-17A as biomarkers or therapeutic targets based on tumor invasion characteristics." (PMID 40725273, 2025). "IL-17A was positively correlated with the expression of PD-L1, which is in line with previous findings that IL-17A was found to induce cellular expression of PD-L1 in hepatocellular carcinoma stem cells, colorectal cancer, estrogen receptor-negative breast cancer, and cholangitis." (PMID 37978543, 2023).